IL10 (interleukin 10)
Diseases named in the same sentence as IL10 in open-access papers (continued):
Sharing a sentence is not in itself a finding about the gene and the disease.
tumor (continued). "The immunosuppressive effect of these M-MDSCs on CD4+ T cells was found primarily to be due to the increased IL-10 production, which in turn, inhibited anti-tumour immune responses, through inhibiting the production of IFN-γ and IL-12, and therefore enhancing tumour growth." (PMID 32931721, 2020). "Furthermore, numerous studies show that, in an appropriate situation, IL-10 can promote IFN-γ production and even increase cytotoxic anti-tumour lymphocytes growth and tumour rejection." (PMID 32397484, 2020). "By specifically releasing IL-10 and TNF-α, TANs reduce the number of lymphocytes and even lead to their dysfunction, such that the outcome of this signaling is a suppressed immunologic reaction at the tumor site." (PMID 33022971, 2020). "In addition, T-reg differentiation is promoted by the production of TGF-β, IL-10 and other mediators including COX-2 and indoleamine 2,3-dioxygenase by stromal and tumour cells." (PMID 32157213, 2020). "In addition, multiple tumor cell injections in the mouse liver metastasis models were found to increase the number of CD4+ CD25 + Treg cells and the expression of cytokines IL-10 and TGFβ-1." (PMID 32408477, 2020). "NK cell proliferation and antitumor activity are suppressed by tumor cell secretion of various immunosuppressive factors, including prostaglandin E2, indoleamine 2,3-dioxygenase (IDO), interleukin 10 (IL-10), transforming growth factor-β (TGF-β), and vascular endothelial growth factor." (PMID 32140153, 2020). "However, M2-like TAMs secrete immunosuppressive cytokines, including IL-10 and TGF-β, which contribute to tumor progression and resistance to chemotherapies in part by inhibiting MHC-mediated antigen presentation and stimulating apoptosis of lymphocytes." (PMID 32424240, 2020). "IL-10 may be produced by the HRS cells, decreasing the natural T cell anti-tumor response, or released by the cells of the surrounding microenvironment in attempt to limit the inflammatory response." (PMID 33276546, 2020). "The biological activity of ANGPT2 is not only restricted to neoangiogenesis but can also impact the macrophage phenotype by promoting PD-L1 expression and IL-10 secretion, which, in turn, are involved in the expansion of CD4+CD25highFoxp3+ Tregs in tumor-bearing mice." (PMID 33168050, 2020). "Consistently, blocking SDHA expression and oxidative phosphorylation activities of macrophages with DMM treatment significantly downregulated the CD206 expressions and MFI of macrophages, but not IL-10 expression in tumor-bearing mice." (PMID 32596169, 2020). "PDL-1 is expressed in tumor cells and antigen-presenting cells, and the engagement of PDL1 with PD-1 of T cell creates T cell dysfunction, exhaustion, neutralization, and interleukin-10 (IL-10) production in a tumor mass." (PMID 32370812, 2020). "Hart and colleagues, showed that IL-10 dictates the immunosuppressive phenotype and function of MDSCs in the tumour microenvironment through interacting with IL-10-receptor (IL-10R) expressed on MDSCs, indicating that MDSC-derived IL-10 expresses autocrine effect on MDSCs themselves." (PMID 32931721, 2020). "Tumor-associated macrophages (TAMs) acquired M2 phenotype could produce cytokines, including IL-6, IL-10, and C-C motif chemokine ligand 20 (CCL20), to reduce anti-tumor immune response and support tumor growth." (PMID 32723346, 2020). "Moreover, widespread cell death triggers efferocytosis-induced wound-healing cytokines, such as IL-4, IL-10, IL-13, and transforming growth factor β (TGF-β), in the TME to further promote metastatic tumor progression." (PMID 32346605, 2020). "These tumours evoked Bregs did not utilise IL-10 dependent suppression but instead primarily functioned to promote the differentiation of Tregs (CD25+) via the TGFβ signalling axis." (PMID 31901949, 2020).
tumor (continued). "IL10 is best studied for its inhibitory action on immune cells such as macrophages, but IL10 can also stimulate CD8+ T cell antitumour immunity and was tested in a clinical trial of multiple tumour types." (PMID 32802517, 2020). "M1-like MDSCs are characterized as tumor-inhibiting cells by the production of TNF-α, IL-12, and nitric oxide, whereas M2-type MDSCs thwart the tumoricidal effect of T lymphocytes or NK cells by secreting TGF-β, IL-10 and arginase." (PMID 32424240, 2020). "IL-10 and TGF-β are considered as the two most important immunosuppressive cytokines in the immune system as they can help tumors escape immune surveillance in the tumor microenvironment." (PMID 32670290, 2020). "Others have described modulation of cytokine production of IL-1α, IL-1β, IL-2, IL-4, IL-6, IL-8, IL-10, IL-17A, TNF-α, and IFN-γ on tumor cells treated with conventional PDT, but their increase or decrease seems to highly depend on the cell line and PDT protocol used." (PMID 32326519, 2020). "For example, Tregs is a subgroup of T cells with negative immune regulation, mainly secreting IL-10 and TGF-β, which can inhibit the activation and proliferation of anti-tumor effector cells and are associated with tumor immune escape." (PMID 33665156, 2020). "Before IL-12 administration, HPV+ tumor cells showed predominant expression of the immunosuppressive cytokines IL-10 and transforming growth factor (TGF)-β1, which could downregulate the immune response favoring tumor implantation." (PMID 32455616, 2020). "IL-10, prostaglandin E2 (PGE2), and TGF-β are examples of signaling molecules, produced by M2-TAMs under the influence of tumor-derived factors, which inhibit T-cell-mediated immune responses and contribute to the establishment of a self-propagating immunosuppressive TME." (PMID 33212945, 2020). "EOC TAM, such as B7-H4+ TAM, are also able to interact with other immunoregulatory cells such as Treg, which in turn stimulate IL-10 and IL-6 production by TAM, further enhancing the immunosuppressive tumor microenvironment and contributing to poor patient outcome." (PMID 32630708, 2020). "Additionally, signaling via C5a–C5aR promotes Treg expansion and suppresses T cell responses in breast cancer metastasis, and increases expression of MCP-1, IL-10, Arg-1, and TGF-β1 in colon cancer tumor metastasis." (PMID 33718121, 2020). "Interestingly, there was an increase in tumor TNF-α and decrease in IL-10 levels in animals treated with fruti, showing a pro-inflammatory effect of fruti." (PMID 33020521, 2020). "PD-L1/PD-1 interaction dysregulates T-cell activity, inducing exhaustion, apoptosis, neutralization, and promoting the production of IL-10, which in turn reduces cytotoxic T-cell (CD8+) activity, promoting cancer development and progression by enhancing tumor cell proliferation and survival." (PMID 32974184, 2020). "Finally, we found that TMEM205 expression appeared to inhibit IL-10 expression (Pearson r = −0.22, p < 0.0001), while TMEM205 expression was positively correlated with the proportion of CD8+ T cells in tumor tissues (Pearson r = 0.26, p < 0.0001)." (PMID 33193690, 2020). "Although many immunosuppressive factors have been recognized so far (e.g., TGF-β, IL-10, IDO), the composition and predominance in different tumor types/stages and the role of costimulation to counteract their negative influence on the antitumor response remain largely to be investigated." (PMID 32504247, 2020). "Furthermore, we reveal an inhibitory role for STAT3 and IL-10 in CD103+ cDC1 vaccine efficacy, as assessed by tumor growth and mouse survival." (PMID 31947933, 2020). "However, tumor cell‐derived cytokines (e.g., VEGF, IL10, and TGF‐β) and inhibitory factors (e.g., galectin‐1, indoleamine 2,3‐dioxygenase, and lipid mediators) are ready to suppress DC maturation and T‐cell activation." (PMID 32976623, 2020).
tumor (continued). "As the tumor progressed, blood leukocytes increased, and erythrocytes decreased leading to a sustained increase in inducible nitric oxide synthase (iNOS), cyclo-oxygenase (COX1), and IL-10." (PMID 33126642, 2020). "Additionally, peripheral blood monocytes with low initial levels of PD-L1 up-regulates the expression of PD-L1, after incubation with primary tumor cells from OSCC patients, which correlates with the increased IL-10 levels in the TME." (PMID 33224886, 2020). "A negative correlation was noted between MCF-7 cell viabilities and M1/M2 cytokine secretion ratios ((IL-6 + TNF-α)/IL-10) in the corresponding MCM, suggesting that increases in M1 macrophages in the tumor microenvironment might inhibit MCF-7 cell growth." (PMID 32308723, 2020). "Kim SJ and Ham JS analyzed the serum cytokines and CD68- and CD163- positive macrophage in tumor tissue of 37 AITL patients after CHOP chemotherapy, and found that high IL-10 and M2 macrophage tissue infiltration all indicated low OS and poor response to treatment." (PMID 33154947, 2020). "The targeting of the immunosuppressive TME cytokines IL-10, VEGF or TGF-ß may effectively reinstate robust anti-tumor immunity by preventing IgG1 to IgG4 class switching and promoting anti-tumor B cell subsets to engage in tumor rejection." (PMID 33569063, 2020). "Previous studies have demonstrated that IL-17 produced by infiltrating immune cells is necessary for initiation and progression of PanIN and that IL-10 secreted by γδ Treg cells diminished the cytotoxic activity of CD8+ T cells and NK cells, resulting in tumor growth." (PMID 32411709, 2020). "Furthermore, the cytokines related to tumor growth, EMT, metastasis and drug resistance, such as IL-1B, IL-2, Il-4, IL-6, IL-10, IL-17, KC (GRO), were mainly expressed in mT obese models." (PMID 32411709, 2020). "In order to indicate whether our proposed therapy method could reduce the level of immunosuppressive cytokines, we measured IL-10 and TGF-ß responses in the tumor microenvironment." (PMID 32782438, 2020). "This was due to secretion by CD4+ T cells of pro-tumor Th2 cytokines (i.e., mainly IL-10 and IL-13), possibly with activation of CD4+ NKT and myeloid suppressive cells, and tumor-derived CCL17 that in turn recruited Tregs already described to have a pro-metastatic role in breast cancer." (PMID 33042121, 2020). "Another analysis showed that in melanoma tumors, SK1 knockdown significantly reduced the production of various immunosuppressive cytokines, such as TGF‐β, IL‐10, CCL17, and CCL22, which was consistent with the explanation of the significant decrease in tumor infiltration of Treg." (PMID 32875727, 2020). "CDDO-Me-mediated effects on TAM IL-10 production may be both direct and indirect, as expression of CCL2 was also significantly blunted by drug treatment in both TAMs and tumor cells." (PMID 32300202, 2020). "Interestingly, CRC patients display Treg cells with a higher expression of several molecules that correlate with suppression, such as Tim-3, LAG-3, TGF-β, IL-10, CD25, and CTLA-4, and by the BLIMP-1 transcription factor expression in the tumor." (PMID 32674255, 2020). "TAMs can also directly inhibit anti-tumour cytotoxic T-cell proliferation and promote regulatory CD4+ T-cell expansion via surface expression of PD-L1, secretion of IL-10 and TGF-β and through the production of nitric oxide and arginase in the same manner as MDSCs." (PMID 32157213, 2020). "A difference was found between male mice with and without primary tumor differed in IL-10 and IL-16 levels, which were higher in those with tumor, and in CXCL5, CXCL11, CXCL13, CXCL16, and CCL24 levels, which were higher in those without tumor." (PMID 32545680, 2020). "Therefore, we determined tumor cytokine expression of type 1 (TNF-α and IFN-γ), type 2 (IL-4 and IL-5), and regulatory (IL-10) cytokines." (PMID 32547942, 2020).
tumor (continued). "Intriguingly, immunosuppressive IL-10 secreting B regulatory 1 (BR1) cells are known to support tumor growth have been shown to have downregulated CD37 (2 fold when compared to IL-10 non-secreting cells)." (PMID 33333768, 2020). "As for humoral factors, VEGF, macrophage migration inhibitory factor (MIF), IL-6, IL-4/13, IL-10, TGFβ, POSTN, colony-stimulating factor-1 (CSF-1), CCL2, CXCL12, and COX-2/PGE2 directly or indirectly regulate the immunosuppressive tumor microenvironment." (PMID 32707672, 2020). "Only SFV4-infected tumor cells consistently induced DCs to secrete Th1 cytokines (IFN-γ, IL-12, TNF-α), Th2 cytokines (IL-4, IL-13), proinflammatory cytokines (IL-6, IL-8, IL-1β,) and anti-inflammatory cytokine (IL-10)." (PMID 31969562, 2020). "Proteins, such as TGFβ, MMP, IL-10, and S100A8/A9, and microRNA are transported by exosomes and play an important role in inducing MDSCs to exert immunosuppressive functions, promoting angiogenesis, and promoting tumor metastasis." (PMID 32942545, 2020). "Cross-linking and tumour antigen-specific IgE antibody-dependent cellular cytotoxicity (ADCC) of cancer cells by cancer patient-derived monocytes triggered release of pro-inflammatory mediators (TNFα, MCP-1, IL-10, CXCL-10, IL-1β, IL-6, IL-23)." (PMID 33203088, 2020). "IL10 directly activates and expands tumor-resident T cells without de novo infiltration from secondary lymphoid organs." (PMID 33381115, 2020). "At the same time, IL-10 can also inhibit the expression of pro-inflammatory molecules, activate Tregs, inhibit CD8-mediated cytotoxic effects, and silence phagocytosis and antibody expression, which is generally beneficial to tumor survival." (PMID 33511267, 2020). "Mutant KRAS could up-regulate immunosuppressive cells in tumor such as myeloid-derived suppressor cells (MDSCs), CD4+FoxP3+ T regulatory cells, and CD19+IL10+ B regulatory cells." (PMID 32206449, 2020). "In the process of tumour immune escape, Tregs can secrete TGF-β, IL-10, and IL-35 (Ebi3-IL-12α heterodimer), which downregulate antitumour immunity, suppress antigen presentation by DCs, CD4+ T helper (Th) cell function and generate tumour-specific CD8+ cytotoxic T lymphocytes (CTLs)." (PMID 32680511, 2020). "Cytokines released from tumor-residing cells including tumor cell–derived IL-4, IL-10, CCL2, CCL3, CCL4, and CSF1; Treg-derived IL-10; B cell–produced immunoglobulins; Th2-derived IL-4 and IL-13; and MSC-derived MFG-E8 promote the polarization into a protumor phenotype." (PMID 31256327, 2020). "MCs also release cytokines such as IL-10, IL-2, IFN-γ which play a direct anti-tumor role." (PMID 32626535, 2020). "Interestingly, the expression levels of IL-10 in the late-stage (stage III and stage IV) tumor tissue were significantly higher in early-stage (stage I and stage II) tumors (p = 0.046)." (PMID 33003428, 2020). "Tumor cell-derived HMGB1 increases the absolute numbers of Tregs in the spleen and draining lymph nodes of tumor-bearing mice, while also stimulating Tregs to produce IL-10 and suppress T cell activation." (PMID 31379812, 2019). "Immunosuppressive cells, including M2-TAMs, myeloid cells, and MDSCs, secrete a variety of cytokines (IL-6, IL-10, IL-4Ra, FasL, CCL2, PGE2, EGF, VEGF, and MMP9) to suppress the function of cytotoxic T lymphocytes (CTLs) and promote the progression of tumour cells." (PMID 30777100, 2019). "Here, we offer an alternative but not mutually exclusive mechanism for enhanced host and anti-tumour immunity, underpinned by the capacity of T cells to generate more IFNγ relative to IL-10." (PMID 30700717, 2019). "Direct injection of boron-rich liposomes into tumor did not have any effect on PBMCs cytokine profile following irradiation which remained as low IL-12 and high IL-10 levels." (PMID 31479484, 2019). "Immunohistochemistry demonstrated IL-10 expression by CD4+CD25+ T cells, but not by tumor associated macrophages or DCs." (PMID 31681327, 2019).
tumor (continued). "In similar fashion within the confines of the tumour, CTLA-4 fosters immunosuppression through the induction and differentiation of Treg cells along with the upregulation of IL-10 and IDO (indoleamine-2,3-dioxygenase) by means of a CD80 and CD86 counter signaling approach." (PMID 30893948, 2019). "In the same way, B cells may play an important role in modulating the tumour response, as they can secrete IL-10 and TGF-β to favour tumour cell proliferation." (PMID 31810265, 2019). "However, expression of other M1/M2 markers (such as CCL2, IL-10, and EGR2) was similar between XO ki and XDH ki tumor infiltrating macrophages." (PMID 31659168, 2019). "Various tumor-derived factors have been reported to induce immature myeloid cells (CD33+ cells) to differentiate to MDSCs, these factors include prostaglandin E2, IL-6, IL-10, IL-1β, TGF-β, and proangiogenic factors such as vascular endothelial growth factor." (PMID 31620141, 2019). "Further, the monocytes primed with tumor-derived exosomes showed following distinct features: a relevant increased of CD206 and IL-10; a clear reduction of HLA-DR, CD64, and IL-12, whereas an significant increased capacity to suppress the proliferation of CD8+ T cells." (PMID 30796203, 2019). "Additionally, IL-34, IL-35, IL-10, IL-4, TGF-β, and CSF-1 promote the differentiation, survival, and recruitment of macrophages into the tumor microenvironment." (PMID 31540435, 2019). "This latter immunisation strategy was more efficacious in preventing tumour growth than immunisation without the IL-10 signalling blockade." (PMID 30897137, 2019). "Thirty days after TC-1 tumour inoculation, mice immunised with the EX/MPLA and IL-10 blockade demonstrated increased inhibition of TC-1 tumour growth compared to mice in groups immunised without the IL-10 signalling blockade or with control antibody." (PMID 31277636, 2019). "Among the tumor-derived soluble factors that contribute to immune cell suppression are vascular endothelial growth factor (VEGF), tumor necrosis factors (TNFs), TGF-β, IL-1, IL-6, IL-10, prostaglandin E2 (PGE2), Fas, and Fas-L." (PMID 31750245, 2019). "Gene expression of IL- 6, IL-10, CCL2, c-Myc, iNOS, CSF-1R, and MMP9 was elevated in all three of the in vitro TAM preparations which suggests that in vitro generated TAM are immunosuppressive and thus tumor promoting." (PMID 31138333, 2019). "Furthermore, co-incubation of CD4+ T-cells with tumor exosomes increased the levels of critical immunological factors such as CTLA-4, TGF-β, IL-10, and COX-2." (PMID 31181729, 2019). "An analysis of immunosuppressive pattern showed significantly increased blood-circulating ARG/IDO/IL-10-expressing M- and PMN-MDSCs in the EOC patients compared with HD and differences in the accumulation of these subsets in the three tumor immune microenvironments (TIME)." (PMID 31001284, 2019). "In patients with HNSCC, tumor infiltrating Treg consistently expressed GITR, FasL, TGFβ, and IL-10." (PMID 31681327, 2019). "UVB-induced B16F10 tumor growth promotion is dependent on an intact immune system, as it is not seen in NOD.CB17-PrkdcSCID/J (NODSCID) mice and is blocked by antibodies to interleukin (IL)-10 and the regulatory T-cell (Treg) marker CD25." (PMID 31212694, 2019). "The first population is stimulated by DC, produces IFN-γ and exerts antitumor activity, the second population is stimulated by endothelial cells specifically for the antigen, produces IL-10 and TGF-β and exerts pro-tumor activity, negatively regulating the activity of the first population." (PMID 31600917, 2019). "Accordingly, pharmacological blockade of C5aR1 in a syngeneic model of lung cancer impaired tumor growth, decreased the percentage of splenic MDSCs, and downregulated immunosuppression-related genes including ARG1, IL6, IL10, CTLA4, LAG3, and PDL1 within the tumor milieu." (PMID 31001273, 2019).